IGLON5 (IgLON family member 5)
Diseases named in the same sentence as IGLON5 in open-access papers (continued):
Sharing a sentence is not in itself a finding about the gene and the disease.
Autoimmunity (16 papers, 2018 to 2026). The occurrence of an immune reaction against the organism's own cells or tissues. "Autoantibodies against IgLON5 (IgLON5-abs) are the hallmark of anti-IgLON5 disease, a recently identified clinical entity in which neurodegeneration and autoimmunity converge." (PMID 37033996, 2023). "Iglon5 parasomnia also has an unusual association with tauopathy linking autoimmunity to neurodegenerative diseases." (PMID 29483905, 2018). "Anti IgLON5 disease is a recently described autoimmune disorder that connects the dots between neuroimmune and neurodegenerative pathology." (PMID 39651491, 2024). "This suggests a potential link between autoimmunity and neurodegeneration in anti-IgLON5 disease, offering a new direction for research into the interrelationship between antibody-mediated neuroimmunity and neurodegeneration." (PMID 38765268, 2024). "The IGLON5 gene participates in regulating sleep and other neural activities and is also related to autoimmunity." (PMID 35847642, 2022). "The special link of RBD with autoimmunity seems more than pure chance, given the important and shared HLA association of RBD and anti-IgLON5 disease, an autoimmune tauopathy." (PMID 36313516, 2022). "Anti‐IGLON5 disease, and possibly NS, offer an opportunity to study the interplay of autoimmunity with later neurodegeneration." (PMID 32775506, 2020). "This differs from other neurodegenerative diseases, where the definite diagnosis relies on neuropathological findings and not on a CSF/blood-based test, and reflects one of the unique features of anti-IgLON5 disease, the combination of autoimmunity and neurodegeneration." (PMID 39400557, 2024). "Anti-IgLON5 disease is a unique condition that bridges autoimmunity and neurodegeneration." (PMID 39400557, 2024). "Finally, we present the current knowledge on IgLON5 disease as a new model of interaction between autoimmunity and neurodegeneration." (PMID 36979644, 2023). "Finally, in the last years, the borders between autoimmunity and neurodegeneration have been further thinned by the discovery of IgLON5 antibodies, which has shed new light on the possible role of autoimmunity in neurodegenerative disorders." (PMID 36979644, 2023). "A 2-year-old boy with anti-IgLON5 autoimmunity was identified, tested with CBA." (PMID 35515348, 2022). "IgLON family member 5 (IGLON5) is related to autoimmunity and neural activities." (PMID 35847642, 2022). "Moreover, IgLON5 antibodies suggest a continuum between autoimmunity and neurodegeneration." (PMID 36979644, 2023). "It is worth noting that our case for the first time showed anti-AMPAR overlapping with IgLON5 after HSE, highlighting that the importance in autoantibody detection should be clinically directive for the parainfectious autoimmunity after viral CNS infection (usually HSV-1 encephalitis)." (PMID 38259458, 2023).
autoimmune disease (15 papers, 2018 to 2026). A disorder resulting from loss of function or tissue destruction of an organ or multiple organs, arising from humoral or cellular immune responses of the individual to their own tissue constituents. "Anti-IgLON5 disease is an autoimmune disorder that has been increasingly recognized in association with lung infections." (PMID 39224609, 2024). "Anti-IgLON5 disease is an autoimmune disease, in which autoantibodies (AABs) against the neuronal cell surface protein IgLON5 lead to profound brain dysfunction and Tau pathology." (PMID 42127169, 2026). "Images are very similar to those shown earlier, confirming the diagnosis as anti-IgLON5 autoimmune disease." (PMID 37603074, 2023). "Only few autoimmune diseases were reported to be associated with HLA-DQB1*05, and these are mostly IgG4-AID, including MuSK MG, pemphigus and anti-IgLON5 disease." (PMID 35654912, 2022). "Anti-IgLON5 antibody-related encephalopathy is a recently discovered and rare autoimmune disease, and its diagnosis and treatment are more challenging than for other autoimmune encephalopathic diseases." (PMID 33731000, 2021). "IgLON family member 5 (Iglon5) is a CNS antigen and is targeted by autoantibodies in Iglon5 parasomnia, which is a severe autoimmune disease characterized by abnormal sleep behavior." (PMID 29483905, 2018). "Anti-IgLON5 antibody-related encephalitis is an autoimmune disease." (PMID 38765268, 2024). "In addition, the massive accumulation of IGLON5 antibodies has been proven to damage the cytoskeleton of hippocampal neurons, which can lead to the occurrence of autoimmune diseases and neurodegeneration." (PMID 35847642, 2022). "Whether IgG4 subclass antibodies to Iglon5 are pathogenic at all is unclear, thus making it a class III IgG4 autoimmune disease." (PMID 29483905, 2018). "Nevertheless, it is important to know that dream enactment behavior may also be observed in narcolepsy, autoimmune diseases (including IgLON5-antibody), or brainstem lesions, as well as with certain medications, mostly selective serotonin or serotonin-norepinephrine reuptake inhibitors." (PMID 37891767, 2023).
Parasomnia (10 papers, 2016 to 2025). A clinically observable or self-reported abnormal behavior, experience, or physiological event that occurs in association with sleep, specific sleep stages, or sleep-wake transitions. "We recently reported a novel neurological syndrome characterized by a unique NREM and REM parasomnia with sleep apnea and stridor, accompanied by bulbar dysfunction and specific association with antibodies against the neuronal cell-adhesion protein IgLON5." (PMID 27358064, 2016). "The anti-IgLON5 case developed a flu-like illness, dysphagia and sleep disturbance likely representing parasomnia." (PMID 33692738, 2021). "We would recommend testing for IgLON5 antibodies only in cases of suspected PSP, which have atypical clinical features, such as stridor, dysphagia, or parasomnias, that are uncommon in PSP patients." (PMID 37646790, 2023). "Given the absence of characteristic parasomnias and of IgLON5 antibodies in CSF, the attribution to IgLON5 disease in the serum-only positive case is uncertain, and alternative etiologies should be considered." (PMID 41262975, 2025). "The clinical phenotype of anti-IgLON5 disease was initially described as bulbar dysfunction, sleep disorders (stridor, obstructive sleep apnea, REM and NREM parasomnias), abnormal movements (myoclonus, chorea, parkinsonism), gait instability, and cognitive decline,62, 66and it continues to expand." (PMID 39706227, 2024).
Encephalopathy (9 papers, 2019 to 2025). Encephalopathy is a term that means brain disease, damage, or malfunction. "Mostly neuronal 3R- and 4R-tau pathology is associated with an autoimmune process anti-IgLON5 (IgLON family member 5)-related encephalopathy that predominantly affects subcortical structures." (PMID 32327993, 2020). "In clinical practice, immunotherapy should be considered in all cases of anti-IgLON5 encephalopathies." (PMID 38450066, 2024). "Furthermore, we used the CSFs of two different patients suffering from IgLON5 encephalopathy as positive controls." (PMID 37603074, 2023). "Among the three anti-IgLON5 encephalopathy patients, one patient had vitiligo." (PMID 31736858, 2019).
Parkinsonism (9 papers, 2017 to 2025). Characteristic neurologic anomaly resulting from degeneration of dopamine-generating cells in the substantia nigra, a region of the midbrain, characterized clinically by shaking, rigidity, slowness of movement and difficulty with walking and gait. "This case underscores the importance of considering Anti‐IgLON5 disease in patients with atypical parkinsonism and diagnostic inconsistencies." (PMID 40542608, 2025). "Anti-IgLON5 disease is a very rare clinical entity characterized by distinctive sleep disorders associated with a broad variety of neurological symptoms, such as parkinsonism with gait instability, bulbar symptoms, and dysautonomia." (PMID 35453897, 2022). "Of note, anti-IgLON5 disease, presenting with supranuclear gaze palsy and parkinsonism, is itself a common differential diagnosis for PSP (14% of cases in a series of 72)." (PMID 41245003, 2025). "Here, we report a case of anti-IgLON5 disease presenting with parkinsonism, falls, sleep problems with severe nocturnal dyspnea attacks, dysphagia, and dysautonomia." (PMID 35453897, 2022). "Indeed, patients with IgLON5 antibodies typically develop a sleep disorder along with bulbar symptoms, parkinsonism, gait abnormalities, oculomotor disturbances, and sometimes cognitive decline, mimicking a PSP clinical presentation." (PMID 41262975, 2025). "Since non-motor features like lack of motivation, retrospectively possibly attributable to anti-IgLON5 disease, had already been present several years before the initial diagnosis of Parkinson’s disease, an even longer duration between symptom onset and final diagnosis could be assumed." (PMID 41008281, 2025). "Despite the presence of vertical SGP in some patients, SGP may also be horizontal and the condition differs from PSP in that parkinsonism tends to be absent with anti-IgLON5 Ab and sleep dysfunction is not a prominent PSP feature." (PMID 28878733, 2017). "Anti-IgLON5 antibodies are the main diagnostic biomarker but the assessment of ocular motor function, particularly in patients with suspected PSP and absence of typical Parkinson’s features, may prompt for anti-IgLON5 antibody testing and support accurate diagnosis." (PMID 34659261, 2021).
Sleep apnea (9 papers, 2016 to 2026). An intermittent cessation of airflow at the mouth and nose during sleep is known as sleep apnea. "A rare autoimmune sleep disorder anti-IGLON5 disease manifests with antibodies towards the IGLON5 protein and causes several sleep problems, including sleep apnea." (PMID 41332830, 2025). "An intronic translocation in Ntm has been implicated in intracranial aneurysms in one family, and auto-antibodies against IGLON5 have been reported in patients with a sleep breathing disorder." (PMID 39073591, 2024). "With heterogeneous clinical manifestations, we found that bulbar dysfunction, sleep apnea, gait instability and neurocognitive and behavioral symptoms are the most common symptoms of anti-IgLON5 disease." (PMID 35620785, 2022).
Ataxia (7 papers, 2020 to 2025). Ataxia refers to impaired coordination of voluntary muscle movement. "Three patients died during follow-up at 3, 9 and 15 months and had anti-IgLON5 disease, paraneoplastic undefined cell surface Ab associated cerebellar ataxia and paraneoplastic anti-GABABR LE respectively." (PMID 34054854, 2021). "The main clinical feature of anti-IgLON5 ataxia is gait instability." (PMID 36138901, 2022). "Unique presenting symptoms of gastrointestinal dysfunction, dysphagia and ataxia were seen in the cases with antibodies against DPPX, IgLON5, and GFAP, respectively." (PMID 33692738, 2021).
Cognitive impairment (7 papers, 2018 to 2024). Abnormal cognition is characterized by deficits in thinking, reasoning, or remembering. "Another example is autoantibodies against the neuronal cell adhesion molecule Ig family containing LAMP, OBCAM, and NTM 5 (IgLON5), which causes a subacute encephalopathy with behavioral abnormalities and sleep disorder, but also cognitive impairment in up to 40% of affected patients." (PMID 39050125, 2024). "Anti-IgLON5 disease was first described as a progressive antibody-associated encephalopathy, with multiple non-specific clinical symptoms including sleep dysfunction, bulbar symptoms, progressive supranuclear palsy-like syndrome, cognitive impairment, and a variety of movement disorders." (PMID 33530233, 2021). "Initiation of immunotherapy in patients with LGI1 and IgLON5 autoantibodies can partially reverse the cognitive impairment, underscoring both, the need for and the potential of early autoantibody diagnostics in presumed neurodegenerative diseases." (PMID 39050125, 2024). "Early testing for IgLON5 antibodies should be considered in patients with atypical neurological symptoms such as cognitive impairment, slow reaction, or decreased orientation." (PMID 38450066, 2024). "Anti-IgLON5 disease is a recently described neurological disorder, characterized by sleep disorders, progressive gait instability, brainstem dysfunction, and cognitive impairment." (PMID 35690819, 2022). "Anti-IgLON5 disease results in a broader spectrum of symptoms, aside from memory and cognitive deficits." (PMID 35690819, 2022).
Chorea (6 papers, 2018 to 2025). Chorea (Greek for 'dance') refers to widespread arrhythmic involuntary movements of a forcible, jerky and restless fashion. "Hyperkinetic movements are frequent in both CNS-WhD (myoclonus, myorhythmia) and anti-IgLON5 (chorea, facial myokymia) and uncommon in PSP, which is primarily characterized by axial parkinsonism, apart from the SGP." (PMID 41245003, 2025). "Other symptoms appeared in heterogenous combinations and the vast majority of anti‐IgLON5 disease patients with chorea described in the literature suffered from a broad spectrum of complaints." (PMID 36698996, 2022). "In an extensive literature review we identified twelve other studies reporting about patients with confirmed anti‐IgLON5 disease and chorea as extrapyramidal movement disorder in their clinical phenotype." (PMID 36698996, 2022). "We discuss the more recently described entities of IgLON5, which has evidence of both immunologic and degenerative pathophysiology, in addition to PDE-10A antibody-associated chorea." (PMID 35370928, 2022). "Movement disorders observed in anti‐IgLON5 disease comprise chorea, tremor, dystonia, parkinsonism, and progressive supranuclear palsy‐like phenotypes." (PMID 36698996, 2022). "Typically, patients with anti‐IgLON5 disease and chorea suffer from additional clinical symptoms." (PMID 36698996, 2022). "Furthermore, an extensive literature search was conducted to compare the clinical phenotypes of reported cases of anti‐IgLON5 disease presenting with chorea as extrapyramidal movement disorder." (PMID 36698996, 2022). "However, focal forms of chorea (craniofacial dyskinesias) or early generalized chorea are present in about 30% of patients, suggesting an alternative diagnosis and representing a clue for IgLON5-Ab disease." (PMID 40274643, 2025). "The combination of PSP clinical features, including rigidity, gait disturbance, and classic absence of vertical OKN, together with extremity chorea, is an unusual presentation of anti-IgLON5 antibody disease." (PMID 41445985, 2025).
cognitive decline (6 papers, 2018 to 2026). "Cognitive decline is a common clinical manifestation of anti-IgLON5 disease and can even lead to dementia in severe cases." (PMID 35300333, 2022). "Anti-IgLON5 disease can present with nonspecific symptoms such as shortness of breath during sleep, cognitive decline, gait disturbance, and autonomic nervous system dysregulation." (PMID 41445985, 2025).
progressive supranuclear palsy (6 papers, 2018 to 2025). A rare late-onset neurodegenerative disease characterized by supranuclear gaze palsy, postural instability, progressive rigidity, and mild dementia. "Sometimes patients with anti-IgLON5 disease present a set of symptoms closely resembling those characteristic for Progressive Supranuclear Palsy (PSP) or even meeting the diagnostic criteria for this condition." (PMID 35300333, 2022). "Comparison of selected symptoms of Homer-3 antibodies positive ACA, Anti-IgLON5 Disease, progressive supranuclear palsy (PSP), multiple system atrophy - cerebellar type (MSA-C), corticobasal degeneration (CBD) and Alzheimer’s disease (AD)." (PMID 40881707, 2025). "Five of them had a classical anti-IgLON5-related brainstem tauopathy and another presented a prominent neuronal and glial 4-repeat tauopathy, consistent with progressive supranuclear palsy (PSP)." (PMID 37646790, 2023). "The movement disorders can be prominent and in 14% of anti-IgLON5 disease patients, initial symptoms may suggest a diagnosis of progressive supranuclear palsy (PSP)." (PMID 37646790, 2023).
Alzheimer disease (5 papers, 2016 to 2025). A progressive, neurodegenerative disease characterized by loss of function and death of nerve cells in several areas of the brain leading to loss of cognitive function such as memory and language. "As in Alzheimer’s disease, the tau filaments seen in the anti-IgLON5 syndrome ultrastructurally appear as paired helical filaments and the differential tau immunohistochemistry confirms that they are composed of both 3R-tau and 4R-tau isoforms." (PMID 27358064, 2016). "Multiple lines of evidence suggest that p-Tau deposits are a primary driver of neurodegeneration in Alzheimer disease, and this may be the case also for anti-IgLON5 disease." (PMID 35326477, 2022). "Anti-IgLON5 disease is a rare disease, but mechanisms involved in neurodegeneration in anti-IgLON5 disease may elucidate broad mechanisms of neurodegeneration in other more frequent forms of neurodegeneration such as Alzheimer's disease and frontotemporal lobar degeneration (FTLD)." (PMID 40930030, 2025).
myasthenia gravis (5 papers, 2021 to 2026). Myasthenia gravis (MG) is a rare, clinically heterogeneous, autoimmune disorder of the neuromuscular junction characterized by fatigable weakness of voluntary muscles. "IgG4-mediated syndromes (e.g., LGI1, IgLON5), Myasthenia Gravis." (PMID 41562781, 2026). "Bulbar dysfunction is a main feature of anti-IgLON5 disease, and its negative impact on survival has previously been demonstrated in other neurological disorders, including anti-IgLON5 disease mimics, such as amyotrophic lateral sclerosis and myasthenia gravis." (PMID 40106089, 2025).
obstructive sleep apnea (4 papers, 2018 to 2025). "The patient presented with typical symptoms of anti-IgLON5 disease such as sleep behavior disorder, obstructive sleep apnea, and daytime sleepiness." (PMID 37383232, 2023). "In all IgLON5-positive patients PSG shows various anomalies such as abnormal sleep architecture, undifferentiated non rapid eye movement (non-REM) sleep or poorly structured stage N2, REM sleep behavior disorder, central hypoventilation, stridor, and obstructive sleep apnea." (PMID 29867738, 2018).
Langerhans cell histiocytosis (3 papers, 2022 to 2024). Langerhans cell histiocytosis (LCH) is a systemic disease associated with the proliferation and accumulation (usually in granulomas) of Langerhans cells in various tissues. "A unique case of a pediatric patient with Langerhans cell histiocytosis (LCH) and co-existing IgLON5 disease has also been described." (PMID 35300333, 2022).
adenocarcinoma of the prostate (2 papers, 2024 to 2025). "For adenocarcinoma of the prostate and for lymphohyperplastic cancer IgLON5 and GAD65 antibodies were detected, respectively." (PMID 38337520, 2024).
Anxiety (2 papers, 2022 to 2024). Intense feelings of nervousness, tension, or panic often arise in response to interpersonal stresses. "Two- month-old IgLON5-KO and wild-type (WT) mice underwent a comprehensive battery of behavioral tests to assess 1) locomotion, 2) memory, 3) anxiety, 4) social interaction, and 5) depressive-like behavior." (PMID 38370417, 2024). "Importantly, memory deficit and anxiety in anti-IgLON5 IgG infused mice persisted until day 32–35, indicating the long-term effects of IgLON5 antibodies." (PMID 35690819, 2022). "In addition, mice injected with anti-IgLON5 IgG embedded in the ventricles showed long-term anxiety-like behavior, which was consistent with the patient’s clinical characteristics." (PMID 35690819, 2022).
Apnea (2 papers, 2016 to 2024). Lack of breathing with no movement of the respiratory muscles and no exchange of air in the lungs. "Anti-IgLON5 antibodies (IgLON5-IgG) from serum and cerebrospinal fluid (CSF) were first described clinically in a cohort of patients with sleep apnoea, non-rapid eye movement (non-REM) and REM parasomnias, and stridor in 2014." (PMID 39063198, 2024).